IL3 (interleukin 3)
Diseases named in the same sentence as IL3 in open-access papers (continued):
Sharing a sentence is not in itself a finding about the gene and the disease.
Sepsis (continued). "It has found that IL-3 influences the progression of inflammatory diseases such as inflammatory bowel disease (IBD), sepsis, and viral infections." (PMID 38702781, 2024). "We chose three proteins as candidate biomarkers, IL-3, IL-6, and PCT, that are known to be elevated in sepsis." (PMID 36129990, 2022). "B cells can produce a large number of pro-inflammatory cytokines such as IL-3, IL-6, GM-CSF, and TNF-α to enhance the systemic inflammatory responses in sepsis." (PMID 36425582, 2022). "Conversely, B1a cells also produce IL-3, IL-6, IL-17, and TNF-α, which play proinflammatory roles in sepsis." (PMID 36425582, 2022). "A cytokine array found that the QX1 formula attenuated sepsis-induced upregulated levels of serum IFN-γ, IL-1β, IL-3, IL-6, IL-17, IL-4, IL-10, and TNF-α." (PMID 32908632, 2020). "As an important upstream cytokine in inflammation, IL-3, also named multicolony-stimulating factor (MSF), plays a crucial role during sepsis; however, its exact role is unclear." (PMID 31568018, 2019). "Surprisingly, the sources of IL-3 during sepsis are the IRA B cell making these cells a producer of two crucial HGFs during sepsis (GM-CSF and IL-3)." (PMID 29977234, 2018). "Furthermore, in sepsis, B cells can produce a variety of pro-inflammatory cytokines like IL-6, TNF, IL-3, and GM-CSF to reinforce the systemic inflammatory response." (PMID 38474403, 2024). "Altogether, these data show that the absence of IL-3 results in reduced protection against HSV-1 infection during sepsis." (PMID 36911737, 2023). "IL-3 blockade had no impact on the mean platelet count or volume kinetics following sepsis but reduced the splenic MK content and proplatelet production." (PMID 35192546, 2022). "LSK and MEP populations and proliferation rates in the BM, blood, and spleen of c-mpl–/– mice, with or without IL-3 blockade, had kinetics similar to that of WT mice during sepsis." (PMID 35192546, 2022). "Our results indicate that splenic megakaryopoiesis in response to sepsis was driven by IL-3, not Tpo." (PMID 35192546, 2022). "To confirm that IL-3, rather than Tpo, drives splenic megakaryopoiesis, we studied MK and platelet responses to sepsis in mice lacking the Tpo receptor (c-mpl–/–)." (PMID 35192546, 2022). "When IL-3 was neutralized in c-mpl–/– mice during sepsis, the MK numbers in the spleen returned to the nonseptic baseline, whereas the BM MK content remained unaffected." (PMID 35192546, 2022). "We found that sepsis triggered adrenergic-dependent mobilization of hematopoietic precursors from the BM to the spleen, where IL-3 rather than thrombopoietin drove maturation of these cells to immune-skewed MKs." (PMID 35192546, 2022). "We found that septic patients either positive for HSV-1, CMV or both in the bronchoalveolar lavage fluid (BALF) showed lower plasma IL-3 levels at the onset of sepsis than septic patients in which no virus was detected in the BALF during the first 28 days of sepsis." (PMID 36911737, 2023). "We showed that mice lacking IL-3 were partially protected from sepsis lethality induced by a CLP." (PMID 29977234, 2018). "Until recently, the role of IL-3 in sepsis was not investigated." (PMID 29977234, 2018). "The gene-downregulating effect of the polyherbal may be of little impact since IL-3-deficient mice had no defect in hematopoiesis, even though IL-3 contributes to leukocyte production, proliferation, and survival, and IL-3 potentiates inflammation in sepsis has been shown." (PMID 35625159, 2022).
leukemia (46 papers, 2009 to 2025). A malignant (clonal) hematologic disorder, involving hematopoietic stem cells and characterized by the presence of primitive or atypical myeloid or lymphoid cells in the bone marrow and the blood. "IGH::IL3 BCP‐ALL represents a distinct subtype of leukemia associated with significant challenges in diagnosis, treatment, and long‐term management." (PMID 40981401, 2025). "Despite its distinct clinical presentation, IGH::IL3‐rearranged leukemia poses numerous diagnostic challenges, primarily due to the low percentage of blasts in the bone marrow and the necessity to exclude much more common reactive hypereosinophilic syndromes." (PMID 40981401, 2025). "Csf2rb encodes a common beta chain of the receptors of interleukin 3, interleukin 5, and granulocyte-macrophage colony-stimulating factor, and its partners’ expression has been described in specifically marking leukemia stem cells." (PMID 34638998, 2021). "METHODS: Murine Ba/F3 leukemia cell lines were stably transfected with distinct FLT3-ITD variants resulting in IL3-independent growth." (PMID 34831215, 2021). "To exclude cell line-specific off-target biology interfering with the effects of kinase-inhibition, we tested leukemia-driving RTK mutations in an isogenic cellular background: Various human (mutant) FLT3 or KIT isoforms were stably transfected in the IL3-dependent murine pro B-cell line Ba/F3." (PMID 23497317, 2013). "Simultaneously, based on animal models, the hyperexpression of CD123, an IL‐3 receptor, on IGH::IL3(+) leukemia cells results not only in their autocrine stimulation but also leads to the Stat5 overactivation." (PMID 40981401, 2025). "Activation of NF-kB upregulates the expression of Interleukin 3 (IL-3) and granulocyte–macrophage colony-stimulating factor (GM-CSF), which in turn provokes the proliferation and survival of stem cells in leukemia." (PMID 35505363, 2022). "The purified hGM-CSF proteins we obtained from E. Coli showed a robust stimulatory effect on the proliferation of TF-1 cells, a human leukemia cell line that responds to multiple cytokines, such as interleukin-3 and GM-CSF." (PMID 34067755, 2021). "Early studies have shown that IL-3 plays a key role in the development of leukemia by allowing leukemia cells to escape programmed cell death and grow autonomously." (PMID 33292550, 2020). "This is in contrast with present studies which show that the complete depletion of Abi1 not only abrogates leukemia development in vivo but also reduces IL3-independent growth in vitro." (PMID 32276588, 2020). "Increased secretion of cytokines, including IL-7 and IL-3, promotes the survival and proliferation of leukemia cells through the activation of the phosphatidylinositol 3-kinase (PI3K) and mitogen-activated protein kinase (MAPK) pathways." (PMID 33105727, 2020). "CSL 360 is a recombinant chimeric immunoglobulin G 1 anti CD123 monoclonal antibody, which can recognize the CD123(+)/CD131(–) phenotype expressed by LSCs exhibiting anti leukemia activity by neutralizing IL-3 to prevent IL-3 binding to its receptor." (PMID 31616632, 2019). "This study used HA-tagged Cebpa constructs transfected into the FDCP1 cell line and an immortalised IL3-dependent murine myeloid cell line that approximates to the wild-type C/EBPα leukaemia line FMH9 that we used for the Myb knockdown studies." (PMID 30877232, 2019). "The FL5.12 cell line represents a well-established interleukin-3 (IL-3) hematopoietic model which has been used to study key genes involved in hematopoietic and leukemia growth." (PMID 29100331, 2017). "In this study, authors are working on conjugation of polymer with IL-3 as the ligand to make a smart nano carrier for leukemia therapy." (PMID 28670519, 2017).
leukemia (continued). "It has been reported that IL-3 receptor(IL-3R) overexpression on leukaemia stem cell populations is a common occurrence, and therapeutic IL-3-IL-3R interference option already shown promising." (PMID 26528857, 2015). "We assessed the relationship between receptor expression levels and responses to each of the cytokines (IL-3, GM-CSF, IL-2, IL-4, M-CSF, G-CSF and IL-6) in leukemia cells from 11 patients with AML." (PMID 26375984, 2015). "Studies are planned to dissect in detail the downstream mediators of IL-3 and v-Abl posttranscriptional control of mRNAs in order to facilitate the development of “post-transcriptional” therapeutics for leukemia." (PMID 19829692, 2009). "Our study identifies a dependency of RUNX1-mutant leukemias on IL-3/JAK/STAT signaling, which may enable targeting of these aggressive blood cancers with existing agents." (PMID 37581927, 2023). "Studies have proven that CD8+ T cells in favorable acute myeloid leukemia (AML) facilitated the growth of leukemia stem/progenitor cells (LSPCs) by way of stimulating the autocrine manufacturing of necessary hematopoietic cytokines such as interleukin-3 (IL-3)." (PMID 35958825, 2022). "In summary, the role of cytokines in leukemia cell survival and proliferation makes IL-3 and IL-7 potential therapeutic targets for obesity-driven B-cell ALL, while IL-7 alone may be a target for obesity-driven T-cell ALL." (PMID 33105727, 2020). "Heightened expression of hematopoietic growth factors such as IL-3 could support leukemia progression through an autocrine mechanism." (PMID 19829692, 2009). "However, the expression of IL3 is poorly detected by RT-qPCR in other leukemia cell lines." (PMID 38566191, 2024). "Here we report that GM-CSF/IL-3/IL-5 receptor common β-chain-associated protein (CBAP) is highly expressed in human T-ALL cell lines and many primary tumor tissues and is required to bolster leukemia cell proliferation in tissue culture and for in vivo leukemogenesis in a xenograft mouse model." (PMID 30266989, 2019). "In the murine bone marrow, IL-3 and IL-7 promote B-cell proliferation and survival and CXCL12 is essential for expanding leukemia cells." (PMID 33105727, 2020). "Leukemia cells transiently expressing mutant SHIP1V684E showed enhanced AKT phosphorylation in response to IL-3 and were resistant to apoptosis, suggesting that SHIP1 can negatively regulate leukemia growth by suppression of AKT activation." (PMID 33276499, 2020). "The MLL-AF9 leukemia cells are highly dependent on IL-3, and it is not surprising that viability declined to some extent among compounds in this class." (PMID 34571009, 2021). "It was shown that using mice NOD/SCID as well as those transgenic for the human cytokines SCF,GM-CSF and IL3 that they were able to develop leukemias with a shortened latency compared mice without human cytokines." (PMID 32529062, 2020). "Validation experiments demonstrated that the negative effect of IL4 on leukemia cell expansion was observed even in the presence of cytokines such as IL3, which gives strong proliferative signals, and without NBM cells present." (PMID 28819278, 2018). "We found that MIF positively influenced survival of KMT2A-MLLT3 leukemia cells when cultured without IL3." (PMID 29720585, 2018). "Cytokines activating STAT5 additionally such as IL-2, IL-3, IL-7, GM-CSF and many others could enhance the effect of BCR-ABL and promote leukemia induction and maintenance." (PMID 28753604, 2017). "In contrast, K14E7 Fancd2+/+ adherent or IL-3 dependent nonadherent cell lines injected S.C. or I.V. produced no leukemia or solid tumors (not shown)." (PMID 27637088, 2016). "And importantly, the IL-3R(CD123) had been considered as a biomarker of leukemia stem cells, although contradictory results exist in the literature that IL-3 has not direct relationship with the hematopoietic stem cells (HSCs), or breast cancer." (PMID 26528857, 2015).
leukemia (continued). "In addition, other cytokines, such as IL-3/15, interferon-α, and platelet-derived growth factor (PDGF), activate STAT6 in diverse cell lines and function in nonimmune systems and the pathogenesis of several diseases, including allergic responses, lymphomas, and leukemias." (PMID 40897694, 2025). "In contrast, a corresponding competition assay in vitro with standard cytokines (interleukin-3 [IL-3], IL-6, and stem cell factor [SCF]) demonstrated that disruption of Cxcr4 in c-Kit+ leukemia cells did not affect cell proliferation." (PMID 32460032, 2020). "The resultant MLL/AF9 leukemia cells could be expanded in vitro without limit in the presence of SCF, IL3, and IL6." (PMID 27011118, 2016).
asthma (34 papers, 2012 to 2025). "Pro-inflammatory cells, such as Il-7 and Il-3, are involved in the pathogenesis of asthma, along with the increase in Th-17 cells, causing an imbalance between Th1 and Th2 cells." (PMID 40648899, 2025). "Since intranasal steroids induce T regulatory cells and IL-3 was found associated with steroid treatment, we next wanted to investigate the role of recombinant IL-3 intranasal (i.n.)in a murine model of asthma." (PMID 35281014, 2022). "Cytokines commonly associated with eosinophilic inflammation in asthma include IL-3, IL-5, eotaxin, and GM-CSF." (PMID 35387066, 2021). "The inflammation caused by asthma is originated from Th2 lymphocytes, which secrete a group of cytokines including IL-5, IL-4, IL-3, IL-13 and GM-CSF." (PMID 32489374, 2020). "This gene set includes numerous cytokines that mediate Th2 cell signaling associated with asthma (IL3, IL4, IL5, IL9, IL10 and IL13), as well as components of the IgE receptor (FCERA, FCERG, MS4A2) and eosinophil granule proteins (ECP, EDN, EPX, and MBP)." (PMID 28854632, 2017). "The study highlighted a significant correlation between high IL-3 levels and subsequent episodes of wheezing, suggesting that these children may be at a higher risk for developing asthma later in life." (PMID 40872787, 2025). "In this research, therefore, we aimed to investigate the effect of IL-3, IL-5, and GM-CSF on the proliferative properties of blood rEOS-like and iEOS-like cells that might be associated with the expression of their receptors in asthma patients." (PMID 36497064, 2022). "Several genes within the cytokine gene cluster on chromosome 5, specifically IL3, IL4, CSF2, TSLP, IL5, RAD50, and IL13, are recognized as potential asthma susceptibility genes due to their roles in inflammatory regulation among sensitized asthma patients." (PMID 41001556, 2025). "IL-3 is known to stimulate the production of basophils and eosinophils, which are key players in allergic responses and asthma pathogenesis." (PMID 40872787, 2025). "IL-3 plays a significant role in the immune response, particularly in the context of airway inflammation and asthma." (PMID 40872787, 2025). "In childhood asthma, an influx of pro-inflammatory IL-17, IL-3, and IL-4, as well as an increase of Th-17 cells and an imbalance of Th1/Th2 cells, are found responsible for the disease." (PMID 37239112, 2023). "In our human study, we describe an increased secretion of IL-3 in the upper airways of children with controlled asthma and PHA-stimulated PBMCs of asthmatic children with A-PC and specifically those children who were treated with steroids." (PMID 35281014, 2022). "Taken together, we found that both the IL-3 and its specific receptor alpha chain were upregulated in controlled asthma." (PMID 35281014, 2022). "By contrast, IL-3 levels in the NPF of asthmatic preschoolers with partially controlled asthma (A-PC) were significantly reduced." (PMID 35281014, 2022). "IL-3 was found downregulated in the nasopharyngeal fluid of children with partially controlled asthma, as compared to control children." (PMID 35281014, 2022). "Here we found that, IL-3 in the NPF of control preschoolers was comparable to the level measured in asthmatic preschoolers with controlled asthma (A–C)." (PMID 35281014, 2022). "These asthma therapies have been directed against interleukin 4/interleukin 13, thymic stromal lymphopoietin, CRTH2 antagonists, and the IL-3/5/GM-CSF axis, and bring the possibility of improved asthma control for patients with severe asthma." (PMID 33917396, 2021). "Glucocorticoids are old anti-inflammatory drugs that have been shown to be very effective in treating asthma and can quickly inhibit the transcription of pro-inflammatory cytokines such as IL-2, IL-3, IL-4, IL-5, and IL-623." (PMID 32760206, 2020). "In asthma and allergic diseases, eosinophil recruitment, survival, and cytotoxic effector functions are largely regulated by IL-5 family cytokines (IL-3, IL-5, GM-CSF)." (PMID 22838633, 2012).